UCP1 (uncoupling protein 1)
Diseases named in the same sentence as UCP1 in open-access papers (continued):
Sharing a sentence is not in itself a finding about the gene and the disease.
tumor (continued). "Histological and immunohistochemical analyses of adipose tissues showed clear signs of browning in iWAT of LLC and C26 but not of C26nc tumor-bearing mice, with reduced adipocyte size, a multilocular lipid droplet phenotype, and increased UCP-1 protein abundance." (PMID 35210363, 2022). "Similarly, a negative correlation between UCP1 expression and tumor hypoxia was confirmed in the analyses using two different scores (refer to the “Materials and Methods” section for details)." (PMID 32647572, 2020). "Another explanation, not necessarily mutually exclusive, is that Minerval has been demonstrated to up-regulate the expression of the uncoupling protein UCP1, thus acting as an OxPhos uncoupler, even though the tumor selectivity of this effect has not yet been tested." (PMID 30602451, 2019). "In the present study of 4011 tumor-free Chinese adults, we observed active BAT located in the cervical-supraclavicular region and the paravertebral region, which have been previously confirmed as the major sites for BAT in adult human by immunohistochemistry with UCP-1 expression." (PMID 25894250, 2015). "Polyclonal antibodies can cross-react with structurally-related molecules so it is possible that staining with the anti-UCP1 antibody of malignant tumour cells in some non-adipose sarcomas could represent a cross-reaction with a UCP1 homologue, such as UCP2 and/or UCP3 in rhabdomyosarcomas." (PMID 31114671, 2019). "Tumour cells strongly expressed FABP4/aP2, a marker of adipocyte differentiation, and UCP1, a marker of brown fat, but not S100." (PMID 29449935, 2018).
cancer (79 papers, 2010 to 2026). A tumor composed of atypical neoplastic, often pleomorphic cells that invade other tissues. "Recent experimental studies on cancer tissue and on the healing tissue beneath burns showed that inflammation, provoked by high level of IL-6, increase expression of UCP1 and predispose to catabolic changes in AT." (PMID 34067093, 2021). "Highly UCP1 expressing cancer-associated fibroblasts were shown to have tumor promoting effects via the generation of high-energy mitochondrial fuels (such as ketone bodies)." (PMID 32120856, 2020). "Most importantly, UCP1 induction elevated cancer cell temperature associated with increased vulnerability to hypoxia and γ-irradiation." (PMID 32647572, 2020). "To examine whether UCP1-CRISPRa mammary adipocytes might prevent cancer development in individuals at high lifetime risk of cancer, we co-cultured them alongside breast organoids from dissected patient-matched breast tissue of BRCA1/BRCA2/RAD51D mutation carriers." (PMID 39905264, 2025). "Thermogenic capacity measured by Ucp1 expression decreased upon cancer in both WAT and BAT (−93% and −63%, p < 0.0044 vs. Ctrls)." (PMID 40237521, 2025). "In BSA-only media, we found that all cancer cell lines that were co-cultured with UCP1-CRISPRa-modulated adipocytes had lower OCR." (PMID 39905264, 2025). "After 3 days, we observed that all five cancer cell lines that were co-cultured with UCP1, PPARGC1A or PRDM16 CRISPRa-treated human adipocytes showed significantly lower cell numbers than cancer cells co-cultured with dCas9–VP64-treated adipocytes." (PMID 39905264, 2025). "In summary, these experiments suggest that UCP1-CRISPRa-modulated adipose organoids outcompete tumors for glucose and fatty acids, as increasing fatty acid or glucose levels abolished cancer suppression." (PMID 39905264, 2025). "Adipocytes engineered to use increased amounts of glucose and fatty acids by upregulating UCP1 were placed alongside cancer cells or xenografts, leading to significant cancer suppression." (PMID 39905264, 2025). "We also observed significantly decreased levels of GLUT4, GCK, CD36 and CPT1b for most of the UCP1-CRISPRa co-cultured cancer organoids, suggesting that they have lower glycolysis and fatty acid metabolism." (PMID 39905264, 2025). "All five cancer organoid cases co-cultured with UCP1-CRISPRa had significantly lower proliferation marker MKI67 expression compared to the negative control." (PMID 39905264, 2025). "A recent study has demonstrated that the UCP1-dependent activation of brown adipose tissue dampens the glycolytic pathways within cancer cells to influence the growth of several cancer types as demonstrated in mouse models and a human study." (PMID 37063269, 2023). "Increased UCP-1 staining in the adipose tissue of cancer cachectic cancer patients showed that increased UCP activity was associated with more thermogenic activity in cancer cachexia and the inhibition of UCPs or the browning of adipose tissue may be beneficial to treat cancer cachexia." (PMID 36900198, 2023). "EAT consists of abundant, small UCP1-expressing adipocytes in a limited space and is scarcely involved in cancer." (PMID 36768479, 2023). "Among them, UCP1 and UCP2 are associated with multiple malignant tumors, including colon cancer, non-small cell lung cancer, pancreatic cancer, and BC." (PMID 35874806, 2022). "This function enables UCP1 to produce a large amount of heat in the brown fat of newborns, while its effect in cancer has been rarely studied." (PMID 36254139, 2022). "Individual cancer stage and node metastasis status showed a similar positive relationship between the expression of UCP1 and better prognosis." (PMID 35541900, 2022). "The Ucp1 mRNA levels were lower in cancer patients vs. controls (p = 0.01), whereas Cidea and Tmem26 mRNA levels were higher in cancer patients." (PMID 35454855, 2022).
cancer (continued). "The results from quantifying the expression data from Western blotting showed significantly increased levels of UCP1 and p-p38/p38 of white adipocytes in the cancer cell-conditioned medium compared to the controls in vitro (p < 0.01, p < 0.001)." (PMID 35893867, 2022). "In particular, unexpectedly, Ucp1 mRNA levels were shown to be decreased in our cohort of cancer patients with respect to controls, as well as among cachectic and non-cachectic patients compared to controls." (PMID 35454855, 2022). "OC-X treatments also caused surge upregulation of several important biomarkers within each cancer progression stage, including UCP1, NOSTRIN, SCGB3A1, ENG, EPAS1, SFTPD, and BMP4." (PMID 34069906, 2021). "Overexpression of UCP1 in brown adipose tissue and UCP3 in skeletal muscle exacerbates weight loss in models of cancer cachexia." (PMID 34627389, 2021). "The relationship between inflammation and UCP1 has been reported in recent studies on cancer and burns." (PMID 34067093, 2021). "In cachexia, a frequent clinical sign in chronic inflammation, cancer, and anorexia nervosa, UCP1 is emerging as a mediator of unwanted wasting of muscle tissue." (PMID 34067093, 2021). "The cancer cells with FABP7 knockdown expressed high level of UCP1 and increased cellular temperature." (PMID 32647572, 2020). "In WAT, browning has been noted in multiple cancer cachexia animal models and in small human studies with adipocytes showing an upregulation of the main regulator of thermogenesis, UCP1." (PMID 32934774, 2020). "Curiously, UCP1 was only expressed in approximately 20–30% of cancer cells even at the highest induction rates." (PMID 32647572, 2020). "In the comparison across the invasive cancer cells, higher-grade tumors had significantly lower UCP1 expression." (PMID 32647572, 2020). "Energy metabolism, fat browning (e.g. uncoupling protein 1), and adipogenesis genes were down‐regulated in cancer VAT (P = 0.043, P = 5.4 × 10−6 and P = 1 × 10−6 respectively)." (PMID 32232960, 2020). "Immunohistochemistry also confirmed the high expression of UCP1 protein in late-stage cancer cachexia." (PMID 29338749, 2018). "White adipose tissue browning, which is associated with increased expression of uncoupling protein 1 (UCP1), increases thermogenesis and energy expenditure during cancer cachexia." (PMID 30275370, 2018). "Taken together, the UCP1-positive cells detected in WAT in both cachectic cancer patients and mice were beige adipocytes." (PMID 29338749, 2018). "For example, the study by Ocker and Höpfner (2012) emphasizes the importance of understanding apoptotic pathways in cancer therapy, suggesting that modulating UCP1 expression could enhance the efficacy of treatments that induce apoptosis in cancer cells." (PMID 41614832, 2025). "We next set out to characterize the effect of UCP1-CRISPRa adipose organoids on various metabolic parameters and test whether resource competition is involved in the observed cancer suppression." (PMID 39905264, 2025). "Furthermore, UCP1 upregulation followed by adipose implantation was recently shown to be beneficial as a cancer therapy." (PMID 41039748, 2025). "Among BAT-activating genes, UCP1 showed the most robust effect in terms of cancer suppression." (PMID 39905264, 2025). "In addition, IL-6, which is a critical inflammation mediator of cancer cachexia driving the expression level of UCP1, is upregulated." (PMID 39519503, 2024). "Stimulation of adipocytes by ADM promotes lipolysis through the phosphorylation of hormone-sensitive lipase (HSL) and uncoupling protein 1 (UCP1) expression in breast adipocytes, which may provide energy to cancer cells or remodel the TME." (PMID 38060103, 2023). "LnCAP, a cancer stem cell line, was used as a positive control of UCP1 expression." (PMID 36005620, 2022). "However, recent reports have shown contradictory results regarding UCP1 expression in adipose tissue in cancer." (PMID 35454855, 2022).
cancer (continued). "Furthermore, WAT biopsies collected from cachectic cancer patients demonstrated extensive UCP1 staining arguing a role for WAT browning." (PMID 35646636, 2022). "Although more studies are needed to elucidate the molecular mechanisms linking FABP7-related fatty acid metabolism and UCP1 induction, our findings illustrate a new metabolic adaption of cancer cells that involves heat production similar to that used by beige adipocytes." (PMID 32647572, 2020). "UCP1 was induced in about 20% of cancer cells, and the effect was increased further in hypoxia." (PMID 32647572, 2020). "However, certain cancers, along with high rate lipolysis, were shown to induce white-to-brown transdifferentiation, named “browning’’, mediated by UCP1, resulting in enhanced fat energy burning with concomitant fat tissue wasting." (PMID 32120856, 2020). "This suggested that FABP7 might be more effective in protecting cancer cells from ROS damage than UCP1." (PMID 32647572, 2020). "However, further investigations are required to understand the precise role of the UCP1-expressing cells and the importance of the adipose metabolic conversion induced by cancer cells during malignancy." (PMID 32819314, 2020). "The low level of UCP1 expression in the tolerant samples may have reflected a high level of natural defenses against cancer via mitochondrial homeostasis." (PMID 30621584, 2019). "To determine whether WAT browning occurred in cachectic patients, we found upregulated UCP1 mRNA in patients with late-stage cancer cachexia compared to the other two groups." (PMID 29338749, 2018). "Our study revealed a higher expression of UCP1, 4 and 5 in rho0 cells and cancer cell lines." (PMID 21935467, 2011). "The induction of UCP1 was firstly considered an adaptive response to cancer induced hypothermia." (PMID 24281083, 2010). "On the other hand, in cancer and CKD the role of the PTHrP/PTH1R axis has also been studied, showing that PTH and PTHrP, through the PTH1R receptor, cause the ‘browning’ of white adipose tissue plus energy production via the activation of uncoupling protein-1 (UCP-1)." (PMID 34827568, 2021). "While UCP1, UCP3, SLC25A27, and SLC25A14 were frequently downregulated in most cancers, UCP2 showed consistent upregulation, indicating divergent functional roles in oncogenesis." (PMID 41403699, 2025). "In this study, the expression levels of UCP1 and IL6 upon cancer cachexia were increased in both adipose tissue and adipocytes; however, this effect was reversed by DOE treatment." (PMID 39519503, 2024). "Several studies have described UCP1 expression, a biomarker of WAT browning, as a critical component of WAT dysfunction in cancer cachexia." (PMID 36499637, 2022). "Although both regulate the expression of UCP-1, PPARγ, PRDM-16, PGC-1α, and other regulatory factors, the effects of nutrients, such as anti-inflammatory, anti-cancer, and anti-oxidation substances, on metabolism are more extensive." (PMID 35886989, 2022). "In concordance with our results, high UCP1 production triggered by IL6 was proposed to be the leading mechanism for lipolysis and cachexia in cancer patients." (PMID 34067093, 2021). "In fact, increased expression of UCP1 in BAT and UCP2 and UCP3 in skeletal muscle have been shown in several murine models of cancer cachexia." (PMID 24281083, 2010). "Uncoupling protein 1 (UCP1), a member of the mitochondrial anion carrier protein (MACP) family, plays an important role in the regulation of membrane potential and lipid metabolism balance in the occurrence and development of various cancers." (PMID 40723842, 2025). "The upregulation of UCP-1, UCP-2, and UCP-3 in BAT and UCP-2 in the skeletal muscle and liver suggested that UCPs were involved in utilizing an excess of fat to induce heat production and thereby increased catabolism and energy expenditure in cancer cachexia." (PMID 36900198, 2023).
cancer (continued). "Thus far, UCP-1, UCP-2, and UCP-3 have been studied in a very limited way in cancer cachexia, and only their expression has been measured and identified, but no drug or molecule has been developed." (PMID 36900198, 2023). "A study evaluating the role of free fatty acid (FFA) receptors FFA1 and FFA4 in cancer cachexia found that UCP-1 was not expressed in the interscapular WAT." (PMID 36900198, 2023). "In accordance with those reports, the disseminated cancer cells mainly attached to and infiltrated UCP1 (a marker for brown adipocytes) negative and Perillipin1 (a marker for pan-adipocytes) positive white adipocytes in the metastatic niche." (PMID 36434071, 2022). "In addition, chronic inflammation is known to increase UCP1 expression and browning of WAT in cancer mice and lipolysis." (PMID 29245988, 2017). "Uncoupling protein-1 (UCP1) IHC staining analysis of gonadal WAT showed an obvious phenotypic switch from white to brown adipose, and the percentage of the brown area increased from 0.11 to 0.29 in cachectic mice (P < 0.01), which is consistent with the previous finding of cancer cachexia in mice." (PMID 40129936, 2025). "In all five cases, we observed a significant reduction in cancer organoid size and, in most organoids, also a reduction in organoid number (TOR124 and TOR41 were not significant) upon incubation with adipocytes infected with UCP1-CRISPRa AAV9 compared to the dCas9–VP64-only treated cells." (PMID 39905264, 2025). "By RT–qPCR, we observed that all cancer cells co-cultured with CRISPRa-treated adipocytes had significantly reduced levels of the proliferation marker MKI67 (other than Panc 10.05 and DU-145 treated with PRDM16 CRISPRa) compared to control cells, with UCP1-CRISPRa having the greatest effect." (PMID 39905264, 2025). "Similarly, in a study involving human cancer patients, those with cancer cachexia exhibited a higher expression of UCP1 in their adipose tissue compared to cancer patients without cachexia." (PMID 37755304, 2023). "Mice lacking UCP-1 was used to study the role of adipose thermogenesis in cancer cachexia." (PMID 35646636, 2022). "Interestingly, different thermogenic pathways independent of UCP1 were described to play a potential role in cancer cachexia." (PMID 35454855, 2022). "Moreover, animal studies have shown that cancer cachexia due to an increased metabolic rate may be mediated by sympathetic stimulation and subsequent BAT thermogenesis with overexpression of UCP1." (PMID 22182284, 2011). "Our data did not reveal changes in the expression of UCP1, a marker of WAT browning involved in the thermogenic waste of energy during cancer cachexia, whereas UCP2 levels were reverted by MitoQ treatment." (PMID 35392166, 2022). "Consistently, gene expression of UCP1 in visceral adipose tissue revealed no significant change with increasing circulating activin A levels in PDAC patients and no significant change between PDAC patients and non-cancer patients." (PMID 35102236, 2022). "Importantly, our findings on increased SERCA ATPase activity in SkM of C26 mice housed at ST, and not at TN, also support the notion that, upon cancer, the increased demand for heat production at ST is met by SkM SERCA‐mediated thermogenesis, and not by Ucp1‐mediated thermogenesis in BAT." (PMID 40237521, 2025).